CT47A8 (cancer/testis antigen family 47 member A8)
Synonyms: CT47.8
Gene: Protein-coding gene on chromosome X (120,948,422 to 120,951,744, reverse strand). Ensembl gene ENSG00000230347.
Subcellular location (Human Protein Atlas): Nucleoli
Homologues: Orthologues: macaque CT47B1 (77% identical). Paralogues in human: CT47A1 (100% identical), CT47A10 (100% identical), CT47A11 (100% identical), CT47A12 (100% identical), CT47A2 (100% identical), CT47A3 (100% identical), CT47A4 (100% identical), CT47A5 (100% identical), CT47A6 (100% identical), CT47A7 (100% identical), CT47A9 (100% identical), CT47B1 (86% identical), and 1 more.
Diseases named in the same sentence as CT47A8 in open-access papers:
CT47A8 is named in the same sentence as 1 disease in open-access papers, as found by Europe PMC text mining. Sharing a sentence is not in itself a finding about the gene and the disease. The quoted sentences say what the papers report.
cancer (1 paper, 2022). A tumor composed of atypical neoplastic, often pleomorphic cells that invade other tissues. "In anal swabs, we found that two genes located on the X chromosome were positively correlated with disease severity, namely, CT47A8 and CT47A4, both of which belong to the cancer/testis antigen family." (PMID 36118230, 2022).